EGFR (epidermal growth factor receptor)
Diseases named in the same sentence as EGFR in open-access papers (continued):
Sharing a sentence is not in itself a finding about the gene and the disease.
tumor (continued). "Collectively, we concluded that blue LED irradiation exhibited anti‐tumour effects on OS by triggering ROS and EGFR/Beclin‐1‐mediated autophagy signalling pathway, representing a potential approach for human OS treatment." (PMID 33960631, 2021). "The 2903 bp deletion polymorphism leads to significantly reduced expression or absence of functional protein containing the BH3 domain and interrupts the apoptosis process of EGFR-mutant tumor cells induced by EGFR-TKIs." (PMID 34722761, 2021). "Avastin-treated mice with and without the supplements exhibited significantly lower levels of epidermal growth factor receptor (EGFR) phosphorylation in tumor tissues than did controls." (PMID 33805447, 2021). "As OV8 tumor cells overexpress epidermal growth factor receptor (EGFR), the targeted LNPs contained anti-EGFR antibody." (PMID 34683969, 2021). "In cancer, epidermal growth factor receptor (EGFR) or its downstream proteins are often overexpressed which promotes tumor growth." (PMID 33923947, 2021). "This is supported as well by a lower expression of the tested tumor markers (EGFR, Neu, cKIT and Ki67), both in preneoplastic and frank lesions developed in both PI3KγKD/KD and PI3Kγ−/− mice." (PMID 34439365, 2021). "Generally, blocking of EGFR signals toward its downstream targets by chemotherapeutic drugs determines the tumor fate." (PMID 34576006, 2021). "Mounting evidence has proved that EGFR impacts the rewiring of the glucose metabolic network to promote tumor progression in NSCLC." (PMID 34155348, 2021). "Osimertinib decreased tumor volume and the EGFR TKI/crizotinib combination further decreased tumor size, which was consistent with previous studies." (PMID 33712615, 2021). "To validate these findings further, we performed a similar analysis on a validation set of tumor samples from 19 independent NSCLC patients with EGFR-WT (n = 9) or EGFR-MT (n = 10)." (PMID 34663810, 2021). "A major focus of this study was to investigate the tumor cell autonomous effects of inhibiting the EGFR/ERBB signaling cascade in HNSCC." (PMID 33485341, 2021). "EGFR vIII is known to promote angiogenesis by activating c-myc and tumor growth by activating signal transducers and activators of transcription (STAT) and P13-Akt pathways." (PMID 34582442, 2021). "In the current study, our findings point to the possibility of exploiting expression of CDCA3 as a strategy to identify TKI responsive EGFR mutant tumours." (PMID 34572879, 2021). "CTX specifically binds with EGFR expressed on the tumor cell membrane and competitively blocks EGF and other ligands, subsequently inhibiting downstream signals." (PMID 34385595, 2021). "It has previously been shown that EphA2 influences NSCLC cell signaling and has an impact on their response or refractoriness to EGFR-TKI treatment as well as upon targeting tumor cell expressed VEGFR2." (PMID 33671073, 2021). "Cytokines which upregulate EGFR signaling, and therefore promote tumor colonization have also been found to be produced by ER-expressing astrocytes following hormonal stimulation in a TNBC model." (PMID 34439289, 2021). "MM-151, an oligoclonal antibody that binds multiple regions of the EGFR ECD, was confirmed to inhibit EGFR signalling and cell growth in a preclinical study and decrease mutations in circulating cell-free tumour DNA (ctDNA) of CRC patients." (PMID 34663410, 2021). "The activity uptake in tumor was noticeably reduced, which confirmed EGFR-specificity of [66Ga]Ga-DFO-ZEGFR:2377 using in vivo imaging." (PMID 33672373, 2021). "This includes tumor gene sequencing as well as the use of specific targeted drugs for tumors with targetable alterations (e.g., EGFR, ALK, ROS1, NTRK, BRAF, or HER inhibitors)." (PMID 34070597, 2021). "Similar to EGFRAP, SOCS proteins, such as Drosophila Socs36E and its human ortholog SOCS5, also contain an SH2 domain, are induced by EGF stimulation and behave as tumor suppressors in cooperation with the EGFR/Ras pathway." (PMID 34411095, 2021).
tumor (continued). "These ligands activate EGFR to stimulate intracellular signaling processes involved in tumor growth and progression, including proliferation, angiogenesis, invasion, and metastasis." (PMID 35082668, 2021). "Overexpression of estrogen receptor β (ERβ) and epidermal growth factor receptors (EGFR) are also reported to play an important role in tumor progression." (PMID 33417986, 2021). "For instance, fusion proteins of anti-EGFR nanobodies conjugated with glycosylphosphatidylinositol (GPI)-anchor signal peptide were utilized to induce targetability of exosomes to EGFR-expressing tumor cells." (PMID 34260047, 2021). "More than half of TNBC patients exhibit the overexpression of epidermal growth factor receptor (EGFR) in tumor cells, and such overexpression is correlated with a poorer prognosis." (PMID 34298600, 2021). "The results indicated that the mutant EGFR pathway facilitated tumor to escape from immune surveillance." (PMID 33413496, 2021). "We also detected elevated DR4 expression in > 60% cases of NSCLC tumor tissues relapsed to treatment with first generation EGFR-TKIs including gefitinib, erlotinib and icotinib." (PMID 33664875, 2021). "EGFR has been used as a tumor biomarker and a drug target for monoclonal antibodies (e.g., cetuximab and panitumumab) and low-molecular weight tyrosine kinase inhibitors (e.g., gefitinib and erlotinib)." (PMID 35052426, 2021). "The combination of EGFR-TKIs and a β-catenin inhibitor abrogates the Notch3-dependent activation of β-catenin, which strongly attenuates tumor onset, improving the OS and RFS of NSCLC xenograft mice." (PMID 34195229, 2021). "It has been shown that suppression of epidermal growth factor receptor (EGFR) signaling in NSCLC correlates with blockade of tumor progression." (PMID 34765548, 2021). "The MR007 PDX model was developed from an osimertinib-resistant EGFR-mutant patient whose drug refractory tumor harbored MET amplification and was found to be sensitive to single-agent savolitinib in vivo." (PMID 34516823, 2021). "These mutations usually occur in older patients (median age of 72 years) with a higher percentage of ever-smokers compared to patients with tumours harbouring other oncogenic alterations such as EGFR/ALK/ROS1." (PMID 34898564, 2021). "To address tumor escape, we generated an EGFR-specific CAR by fusing monoclonal antibody (mAb) 806 to a 4-1BB co-stimulatory domain." (PMID 34568006, 2021). "In particular, the location of the primary tumor is now known to affect the outcomes of EGFR-targeted therapies, with left-sided tumors seemingly responding better." (PMID 34199694, 2021). "Univariate analysis of TCGA database and our tumor banks showed that amplification of LANCL2 or EGFR, and their co-amplification were significantly correlated with poor OS, but not PFS of GBM patients." (PMID 34461927, 2021). "It was shown to have an acceptable risk–benefit profile and encouraging anti-tumor activity in MET-amplified, EGFR mutant positive, advanced NSCLC patients." (PMID 34238332, 2021). "Post-CAR T-treated tumor specimens showed continued presence of EGFR amplification and oncogenic EGFR extracellular domain (ECD) missense mutations, despite loss of EGFRvIII." (PMID 34568006, 2021). "In case of PE/CA-PJ41 cells harboring the wild type EGFR, cetuximab showed dramatic inhibitory effect on the tumor growth: tumors were completely eradicated upon treatment with all combined therapeutic combination containing the monoclonal antibody." (PMID 34257586, 2021). "Immunohistochemical staining of proliferating cells in tumor tissues showed notably lower numbers of EGFR-high cells in the cetuximab-treated group." (PMID 32989241, 2021). "MSA treatment significantly decreased the tumor burden and EGFR protein expression in tumor specimens." (PMID 34393797, 2021).
tumor (continued). "This leads to an extremely interesting question: Do EGFR inhibitors affect patient tumor progression and regression fate?" (PMID 33787673, 2021). "In a parallel EGFR pathway, radioresistance of tumor cells that overexpress Rab5C, Ku70, and Ku80 was traced to Rab5C regulation of EGFR internalization and its translocation to the nucleus, where EGFR stimulates Ku70/Ku80 expression." (PMID 34337349, 2021). "Phosphorylation of MET induces the activation of PI3K/AKT and RAS/RAF/MAPK cascades to rescue tumour cells from EGFR inhibitors." (PMID 34663410, 2021). "Third, microarray analyses of cultured pNET cells expressing or lacking RABL6A identified a RABL6A-regulated gene expression profile that included activation of c-Myc, VEGFR, and EGFR pathways, all of which are major mediators of tumor angiogenesis." (PMID 34199469, 2021). "Among them, the EGFR/PI3K/AKT pathway indirectly regulates tumor cell apoptosis through maintaining the balance between cell proliferation and apoptosis." (PMID 34975466, 2021). "Decisions regarding the use of EGFR-directed therapies are typically made based on molecular testing of the initial tumor pathology or via liquid (blood) biopsy." (PMID 35201504, 2021). "For example, a reduced benefit of EGFR‐TKI therapy has been associated with increasing levels of sensitizing mutations in ctDNA, likely reflecting an increase in systemic tumor burden and/or overall tumor activity." (PMID 34296539, 2021). "Não houve correlação significante entre o status mutacional do RAS e a expressão de EGFR em relação a idade, gênero, local do tumor, tipo histológico, grau histológico e estádio clínico." (PMID 34133521, 2021). "A recent study has identified EGFR involvement in the suppression of tumor suppressor‐like miRNA maturation in response to hypoxic stress through phosphorylation of argonaute 2 (AGO2)." (PMID 33605506, 2021). "These include low PD-L1 expression on tumor cells and TILs, low tumor mutation burden (TMB) and immune escape using other immune checkpoints in patients with EGFR-mutant NSCLC." (PMID 34488906, 2021). "The EGFR pathway has emerged as a key anticancer target for blocking the invasion and proliferation of tumor cells." (PMID 34147083, 2021). "In this work, we have engineered EGFR and NKp30 targeting cattle-derived bispecific common light chain antibodies that can be utilized to efficiently redirect NK cells in order to kill EGFR-overexpressing tumor cells." (PMID 35087526, 2021). "In contrast, the comprehensive work of the Nijmegen group demonstrated that EGFR-expression is present mainly in oxygenated areas of HNSCC tumor specimens near blood vessels." (PMID 33718186, 2021). "We therefore placed the samples into five groups (scores of 0–4) according to the percentage of tumour cells in which EGFR was localized primarily to the cell membranes." (PMID 35008337, 2021). "EGFR and Src are key role players in the mitogenic and motogenic effects in M subtype as well and regulate many aspects of tumor behavior including cell proliferation, migration and angiogenesis." (PMID 33802438, 2021). "Another important factor to consider is the high rate of mutation of tumor-promoting proteins such as KRAS and EGFR in signaling pathways causing acquired resistance to targeted therapy." (PMID 34162394, 2021). "The most important imaging marker was the ratio of contrast enhancing volume to the necrotic tumor volume, which correlated with EGFR expression." (PMID 34298788, 2021). "Signaling of epidermal growth factor receptor (EGFR) in TNBC, which activates Src kinase activation, is one of the major causalities of tumor progression." (PMID 34128588, 2021). "The GE11 peptide has been demonstrated to promote tumor penetration and selectively bind to the epidermal growth factor receptor (EGFR), a typical overexpressed receptor in epithelial origin tumors." (PMID 34277592, 2021).
tumor (continued). "The combination treatments of BRAF inhibitors (vemurafenib) and EGFR inhibitors, namely gefitinib, erlotinib, or cetuximab, in patients with CRC synergistically inhibited mutated BRAF V600E (BRAFV600E) tumor growth in xenograft models." (PMID 34884633, 2021). "In EGFR-dependent cancers of multiple cell lineages, FGFR3-TACC3 fusion proteins are also characterised as “naturally occurring drivers of tumour resistance” by reactivating EGFR/ERK signalling." (PMID 34830836, 2021). "After progression, patients with RAS/BRAF WT tumor according to liquid biopsy will continue EGFR blockade while changing chemotherapy backbone (FOLFOX)." (PMID 33920531, 2021). "The association of cetuximab with both an EGFR-expressing HNSCC cell and an FcγR-expressing immune cell provides a bridge, inducing antibody-dependent cellular cytotoxicity (ADCC) and subsequent tumor cell elimination." (PMID 34681717, 2021). "About the demographic data between the different EGFR phenotypes, the distribution of gender, smoking condition and tumor cell differentiation status demonstrated significant difference between the two groups." (PMID 33799753, 2021). "We compared these agents to the tyrosine kinase inhibitor erlotinib or to dox withdrawal, which both induce rapid tumor regression by inhibiting EGFR phosphorylation and turning off oncogenic EGFRL858R, respectively." (PMID 34494649, 2021). "EGFR and its family members play a variety of roles in the aberrant growth, oncogenesis and tumor progression in different cancers and cell types." (PMID 33535661, 2021). "In fact, several co-mutations associated with mutations in EGFR have been shown to bring about a lower efficacy to EGFR TKIs, to give tumor resistance to these molecules, and to result in a poorer prognosis." (PMID 34440926, 2021). "This study shows a significantly reduced progression-free survival in patients with high (nuclear) ERα (and EGFR) tumor levels." (PMID 34830915, 2021). "EVs can affect the extracellular matrix (ECM) by modulating tumor immunity responses and can even transfer active oncogenes, e.g., EGFR or the mutant form of KRAS." (PMID 34684727, 2021). "Inspired by the pronounced EGFR activities and the antitumor activities of these derivatives in vitro, we next determine the in vivo antitumor efficacy using mouse tumor models." (PMID 35071184, 2021). "Intracellular EGFR accumulation frequently occurred in CYLD-expressing tumours, which suggested active endocytosis." (PMID 35008337, 2021). "Analysis of tumor burden showed that in EGFR mice, osimertinib efficiently controlled EGFR tumor growth, with a three-fold decrease in the percentage of tumor cells (52% in vehicle-treated and 17% in osimertinib-treated mice)." (PMID 34298655, 2021). "EGFR-mediated autophagy exerts relevant roles in gliomagenesis, tumor progression, and therapy resistance." (PMID 34178638, 2021). "Taken together, these findings suggest that the c-MET/EGFR system is an important mediator within the tumor microenvironment (TME) that results in enhanced tumor growth." (PMID 34512327, 2021). "Vandetanib has been found to be effective in inducing in vivo tumor regression in TNBC PDX models with high expression of RET or EGFR with concordant suppression of RET/EGFR phosphorylation and MEK/ERK pathway activation." (PMID 34207383, 2021). "Most importantly, LCP Pyro PA NPs enhanced EGFR siRNA gene therapy, resulting in a significant decrease in tumor volume (p < 0.01) compared with the four other experiment groups." (PMID 34575510, 2021). "As a result, early signaling downstream of the TCR promotes T cell activation and leads to lysis of EGFR-positive tumor cells." (PMID 34832954, 2021). "Patients experiencing tumor progression with BRAF genetic alteration as an ARM to osimertinib in EGFR-mutant NSCLC usually receive platinum-based chemotherapy." (PMID 34575554, 2021).
tumor (continued). "Here we investigate the effect of anti-EGFR therapy on survival in different consensus molecular subtypes (CMSs) and stratified by primary tumour location." (PMID 34253874, 2021). "Our research demonstrates significant differences in tumor microenvironment composition between EGFR-mutant and wild-type patients." (PMID 34484468, 2021). "Age of patients with wild-type IDH1 and EGFR increased with increase in tumour grade, while the age of patients with IDH1 or EGFR mutation remained constant." (PMID 34205437, 2021). "Our results raise the possible role of other RTK-stimulated pathways, and the involvement of the anti-EGFR antibody induced cytotoxic immune response in tumor elimination." (PMID 34257586, 2021). "EGFR hyperactivation occurs in many tumor types, through strategies such as receptor overexpression, autocrine stimulation, or constitutive active receptor mutants." (PMID 33321449, 2021). "In vivo data revealed anti-tumor activity of NA49 with cisplatin in EGFR-WT cells or with Gef in EGFR-Mut cells, indicating NA49 as an adjuvant candidate for anticancer therapy." (PMID 33925114, 2021). "EGFR, ErbB2, and ErbB3 are all endogenously expressed in rat lacto-somatotroph tumor cells, and in vitro treatment with EGFR TKIs was shown to prevent PRL secretion." (PMID 34867776, 2021). "Further results in this study showed in vitro and in vivo that the combination of vemurafenib and erlotinib (an EGFR inhibitor) leads to a dramatic tumor response, and an improved inhibition of tumor cell proliferation." (PMID 34063682, 2021). "After identifying EGFR as a target candidate, we modulated the gene expression and inhibited its kinase activity to determine its functional importance in tumor cell clustering and therapeutic inhibition of lung metastasis." (PMID 33995681, 2021). "Recombinant anti-EGFR CAR-T cells have specific cytolytic activity against EGFR-positive tumor cells." (PMID 33025047, 2021). "The in vivo specificity of [66Ga]Ga-DFO-ZEGFR:2377 binding to EGFR in tumor xenografts was evaluated by pre-saturation of receptors using the monoclonal anti-EGFR antibody cetuximab, which binds to the same epitope as ZEGFR:2377." (PMID 33672373, 2021). "As expected, all seven cattle-derived common light chain bsAbs showed specific binding to EGFR-overexpressing tumor cell line A431 with similar mean fluorescence intensities (left)." (PMID 35087526, 2021). "Tumor heterogeneity is an important reason for the efficacy and resistance to EGFR targeted therapy in patients with NSCLC." (PMID 34970478, 2021). "In line, an average between‐group difference of 7.4% was observed when tumor cells were exposed to an EGFR‐mAb." (PMID 34110712, 2021). "Another study used an epidermal growth factor receptor (EGFR) specific aptamer conjugated to hollow gold nanospheres (HAuNS) to target an EGFR positive tumor cell line." (PMID 34770931, 2021). "This decrease in tumor volume was mediated by decreasing the tumor’s response to growth factors via downregulation of the EGFR." (PMID 34638282, 2021). "TERT promoter mutations generally occur late in tumor genesis, after the appearance of driver mutations in other oncogenes such as RAS/BRAF, EGFR, which lead to constitutive cell division and thus accelerate telomere erosion." (PMID 34944589, 2021). "CAR T cells designed with anti-Her2 DARPin or DARPins specific for Her2, epidermal growth factor receptor (EGFR), and epithelial cell adhesion molecule (EpCAM) showed potent tumor regression in preclinical models." (PMID 34209505, 2021). "Tumor cells positive for EGFR have a high degree of malignancy and are prone to invasion and metastasis." (PMID 34591414, 2021). "Changes in the histology of the tumor have been increasingly recognized as a critical mechanism of resistance to EGFR-directed therapies." (PMID 34572868, 2021).